ZDHHC16 (zDHHC palmitoyltransferase 16)
Description:
Palmitoyl acyltransferase that mediates palmitoylation of proteins such as PLN and ZDHHC6. Required during embryonic heart development and cardiac function, possibly by mediating palmitoylation of PLN, thereby affecting PLN phosphorylation and homooligomerization (By similarity). Also required for eye development (By similarity). Palmitoylates ZDHHC6, affecting the quaternary assembly of ZDHHC6, its localization, stability and function. May play a role in DNA damage response (By similarity). May be involved in apoptosis regulation (By similarity). Involved in the proliferation of neural stem cells by regulating the FGF/ERK pathway (By similarity).
Synonyms: DHHC-16; APH2
Tractability: Antibody: UniProt predicts a signal peptide or a membrane-spanning region. PROTAC: ubiquitination databases record sites on it.
Gene: Protein-coding gene on chromosome 10 (97,446,142 to 97,457,370, forward strand). Ensembl gene ENSG00000171307.
Subcellular location: Endoplasmic reticulum membrane
Subcellular location (Human Protein Atlas): Nucleoplasm; Cytosol; Nuclear membrane
Gene Ontology:
Molecular function: palmitoyltransferase activity; protein binding; protein-cysteine S-palmitoyltransferase activity
Biological process: DNA damage response; eye development; heart development; telencephalon development
Cellular component: Golgi apparatus; endoplasmic reticulum membrane
Genetic constraint (gnomAD): Loss-of-function variants: 33 observed, 55.51 expected, observed/expected ratio (o/e) 0.59, 90% interval 0.45 to 0.8. The upper end of that interval is the gene's LOEUF score, 0.8, which puts it in group 3 of 6, group 1 being the genes least tolerant of losing a copy. Missense variants: 419 observed, 508.93 expected, observed/expected ratio (o/e) 0.82, 90% interval 0.76 to 0.89. Synonymous variants: 185 observed, 192 expected, observed/expected ratio (o/e) 0.96, 90% interval 0.85 to 1.09.
Homologues: Orthologues: rat Zdhhc16 (99% identical), rabbit ZDHHC16 (99% identical), chimpanzee ZDHHC16 (98% identical), dog ZDHHC16 (98% identical), macaque ZDHHC16 (98% identical), pig ZDHHC16 (98% identical), guinea pig ZDHHC16 (97% identical), mouse Zdhhc16 (95% identical), tropical clawed frog zdhhc16 (66% identical), zebrafish zdhhc16b (58% identical), zebrafish zdhhc16a (53% identical), Drosophila melanogaster CG5880 (42% identical).
Diseases named in the same sentence as ZDHHC16 in open-access papers:
ZDHHC16 is named in the same sentence as 10 diseases in open-access papers, as found by Europe PMC text mining. Sharing a sentence is not in itself a finding about the gene and the disease. The quoted sentences say what the papers report.
glioblastoma (2 papers, 2023 to 2025). The most malignant astrocytic tumor (WHO grade IV). "ZDHHC16-mediated SETD2 palmitoylation has been shown to promote DNA damage in EGFR-mutated glioblastoma." (PMID 40814339, 2025). "Notably, ZDHHC15 and ZDHHC16 are primarily reduced in brain cancers, particularly glioblastomas." (PMID 38067206, 2023).
glioma (1 paper, 2023). A benign or malignant brain and spinal cord tumor that arises from glial cells (astrocytes, oligodendrocytes, ependymal cells). "The survival time of glioma patients with low expression of zDHHC16 and high expression of epidermal growth factor receptor was shorter than that of patients with high expression of zDHHC16 and low expression of epidermal growth factor." (PMID 38293675, 2023). "In glioma tissue, not all abnormal zDHHCs were overexpressed compared to those in normal brain tissue, and zDHHC16 was significantly downregulated compared to that in normal brain tissue." (PMID 38293675, 2023).
ovarian carcinoma (1 paper, 2024). A malignant neoplasm originating from the surface ovarian epithelium. "In ovarian cancer, ZDHHC16 was the dominant enzyme for palmitoylation by claudin 3 (CLDN3)." (PMID 38532349, 2024). "Through palmitoylation, ZDHHC16 stabilizes the CLDN3 protein and promotes the incidence and growth of ovarian cancer." (PMID 38532349, 2024).
periodontitis (1 paper, 2024). An acute or chronic inflammatory process that affects the tissues that surround and support the teeth. "We identified that inhibition of ZDHHC16 reduced DPSCs ferroptosis, demonstrating that it may be a treatment target for DPSCs OD or periodontitis treatment by regulation of ferroptosis." (PMID 38532349, 2024). "So ZDHHC16 may be a marker of OD and a potential treatment target for osteogenic differentiation of DPSCs or the treatment of alveolar bone defects by periodontitis." (PMID 38532349, 2024).
viral infection (1 paper, 2024). "ATG14 and ZDHHC16 (zinc finger DHHC-type containing 16) may indicate the engagement of autophagy-related pathways and membrane trafficking adjustments as cellular strategies against viral infection." (PMID 38655085, 2024).
cancer (1 paper, 2021). A tumor composed of atypical neoplastic, often pleomorphic cells that invade other tissues. "Consistent of results of online database, ZDHHC16 was upregulated in cancer cells relative to normal cell." (PMID 33794886, 2021).
cardiovascular disease (1 paper, 2021). "Calnexin is an ER chaperone that has been implicated in cardiomyocyte viability and in ER stress, a prominent clinical feature of cardiovascular disease, while ITPR1 mediates the influx and release of intracellular Ca2+ and is regulated by the palmitoylation cascade of ZDHHC16/ZDHHC6." (PMID 34252155, 2021).
tumor (1 paper, 2021). "ZDHHC16 expression was significantly positive associated with clinicopathological stage, tumor grade and ICB immunotherapy key genes (i.e., CD274, CTLA4, HAVCR2 and PDCD1, etc.)." (PMID 33794886, 2021). "Collectively, subjects with higher risk score or higher ZDHHC16 expression level presented more abundance of immune cells in tumor environment, suggesting activated immune phenotype, but shorter overall survival time." (PMID 33794886, 2021). "Then the correlation between the ZDHHC16 and ICB key targets adjusted by tumor purity using TIMER was analyzed to investigate the potential player of ZDHHC16 in ICB treatment of HCC." (PMID 33794886, 2021). "ZDHHC16 expression level between normal tissues and tumor samples was compared based on TCGA data." (PMID 33794886, 2021). "Relative to tumor tissues, ZDHHC16 expression level was lower in adjacent normal specimens." (PMID 33794886, 2021).
ZDHHC16 also shares sentences with these, for which no sentence is quoted: pancreatic cancer (1 paper); Sepsis (1).